CXorf58 (chromosome X open reading frame 58)
Synonyms: FLJ25444
Tractability: PROTAC: ubiquitination databases record sites on it.
Gene: Protein-coding gene on chromosome X (23,907,807 to 23,939,509, forward strand). Ensembl gene ENSG00000165182.
Subcellular location (Human Protein Atlas): Nucleoplasm
Gene Ontology:
Molecular function: protein binding
Homologues: Orthologues: chimpanzee CXorf58 (97% identical), macaque CXHXorf58 (95% identical), pig CXorf58 (63% identical), dog CXorf58 (61% identical), rabbit CXorf58 (59% identical), rat Cxhxorf58 (56% identical), mouse Fam90a1b (55% identical).